ICOS (inducible T cell costimulator)
Diseases named in the same sentence as ICOS in open-access papers (continued):
Sharing a sentence is not in itself a finding about the gene and the disease.
tumor (continued). "With respect to target engagement, feladilimab exhibited dose-dependent receptor occupancy in A549 tumor-bearing mice and, comparable with our observations with the mIgG1 anti-ICOS mAb in EMT6 tumor-bearing mice, significantly increased the CD8:Treg cell ratio in the tumor." (PMID 37593752, 2023). "Targeting ICOS and CTLA4 together was demonstrated to promote the anti-tumor effect, and the expression of ICOS could serve as a biomarker for predicting the efficacy of anti-CTLA4 therapy." (PMID 38127899, 2023). "Both ICOS+Foxp3+ Treg cells and pDCs in peripheral blood and tumor tissue could predict poor clinical outcome in GC patients." (PMID 35311157, 2022). "Surgically resected UPS samples were stained by immunohistochemistry (IHC) for the following: tumor-associated immune cells (CD3, CD8, CD163, CD20), immune checkpoints (stimulatory: OX40, ICOS; inhibitory: PD-L1, LAG3, IDO1, PD1), and the adenosine pathway (CD73, CD39)." (PMID 36313661, 2022). "Activated tumor-infiltrating Tregs (CD4+Foxp3+ICOS+Ki67-; cluster 13) were also significantly reduced in both combination chemo‐immunotherapy treated groups (5-FU+ICB: 0.25 ± 0.20%; cisplatin+ICB: 0.29 ± 0.31%) compared to PBS controls (2.73 ± 1.01%; p = 0.015; p = 0.014 respectively)." (PMID 35634282, 2022). "ICOS+ Tregs could produce a mass of IL‐10 and TGF‐β1,155 and the levels of tumor‐infiltrating ICOS+ Tregs were higher than those in tumor adjacent tissues in several cancers." (PMID 35474948, 2022). "Moreover, pDCs were mainly distributed in peritumor tissue, whereas Treg cells and ICOS+ Treg cells were mainly distributed in tumor tissue." (PMID 35311157, 2022). "Furthermore, ICOS was significantly decreased on the surface of circulating and tumour-infiltrating CD8+ T cells compared with the treatment-naïve setting in OAC patients." (PMID 35366537, 2022). "In contrast, tumor angiogenesis (CD31) was also decreased in animals treated with IL ICOS-Fc." (PMID 36500861, 2022). "ICOS was significantly deceased on tumour-infiltrating CD8+ T cells post-FLOT treatment." (PMID 35366537, 2022). "To determine whether these changes in ICOS expression in the peripheral blood were also reflected in the tumor, we harvested tumors at day 21 (day 7 following radiation therapy) to evaluate ICOS expression on tumor-infiltrating T cells by flow cytometry." (PMID 36056093, 2022). "These included key genes associated with cytotoxic anti-tumor T cell responses (GZMA, GZMB, PRF1), co-stimulation of T cells (CD27, CD28, ICOS), and genes associated with other immune processes, including Type I IFN response (TNF, TNFSF10), as well as T cell exhaustion (CTLA4)." (PMID 36698398, 2022). "ICOSL triggering mediated by ICOS drives a “reverse signal” that inhibits the migration of endothelial, dendritic, and tumor cells, modulates cytokine secretion while promoting antigen cross-presentation in dendritic cells, and inhibits osteoclast differentiation and functions." (PMID 35806368, 2022). "In addition, anti-CTLA-4 increases the intra-tumoral Teffector: Treg ratio by promoting the expansion of ICOS+ effector T-cells in favor of anti-tumor activity." (PMID 35326731, 2022). "By contrast, ICOS antibody treatment decreased T regulatory cells in the tumor when used as a single agent and also in combination with RT (ICOS Ab vs. Isotype p < 0.01; RT + ICOS Ab vs. RT p < 0.01), in line with the reported Treg depletion activity of this antibody in preclinical studies." (PMID 36056093, 2022). "However, the roles of ICOS across different types of malignancies are inconsistent, mainly due to the dualistic effect of ICOS in the tumor microenvironment." (PMID 36276141, 2022). "There were more ICOS+ Tregs in tumor and peritumor tissue of late-stage GC patients." (PMID 35311157, 2022). "PD-1+ and ICOS+ TILs are enriched for tumor-reactive CD4+ Th cells." (PMID 35439168, 2022).
tumor (continued). "Moreover, in the tumor microenvironment, Tregs express increased levels of ICOS and Foxp3 and secrete higher levels of IL-10 and TGF-b." (PMID 36591244, 2022). "Indeed, ICOSL triggering by OPN induces tumor cell migration and promotes tumor angiogenesis, both of which are counteracted by ICOS-mediated activation of ICOSL." (PMID 35806368, 2022). "Interestingly, there was a significant decrease in the expression of ICOS on the surface of tumour-infiltrating CD8+ T cells post-FLOT compared with the treatment-naïve setting (p = 0.01)." (PMID 35366537, 2022). "Protein expression comparisons of immune and tumor cells reveal that PD-L1 was predominantly expressed on tumor cells, while ICOS, IDO-1, LAG-3, and OX40 were predominantly present on immune cells, and TIM-3 and VISTA were expressed on both tumor and immune cells in similar proportions." (PMID 34093591, 2021). "Notably, all six expression-based markers for human TI-Tregs, TIGIT, TNFRSF9, ICOS, CCR8, CD83, and CCRL2, were ranked within the top 10%, which indicates that they are likely to play major roles in tumor-associated Treg functions." (PMID 33598101, 2021). "Just as the CD28/B7-binding protein family has inhibitory checkpoints, it also includes stimulatory checkpoints, one of which is inducible co-stimulator, or ICOS, expressed mainly on T-cells, with its counterpart ICOS-ligand (ICOS-L) expressed by DCs, macrophages and sometimes tumor cells." (PMID 32867025, 2020). "We also identified a novel role for FAK in regulating the expression of ICOS, primarily on CD8eff T-cells, and showed that blocking ICOS ligand could impair the anti-tumor efficacy of both FAK/anti-OX40 and FAK/anti-4-1BB combinations." (PMID 31959281, 2020). "Signaling through ICOS has been reported to enhance the anti-tumor efficacy of OX40." (PMID 31959281, 2020). "Moreover, Tregs in TDLNs and in the tumor expressed high levels of CTLA-4, ICOS, GITR, and OX40, phenotype associated to a high suppressive capacity." (PMID 32601304, 2020). "The ICOS-driven interaction between tumor associated CD4+ T cells and ICOSL-expressing TA-pDCs sustain the expansion of ICOS+ FoxP3+ Tregs in the tumor microenvironment and promote the secretion of IL-10 and TGF-β from Tregs, which support an immunosuppressive microenvironment and tumor progression." (PMID 32054102, 2020). "ICOS is a T-cell co-stimulator that enhances T-cell responses including proliferation and lymphokine proliferation; thus, it may mediate host anti-tumor immunity." (PMID 32313087, 2020). "While tonic signaling appeared to be dependent on the proximity of 4-1BB to the cell membrane, the enhanced anti-tumor efficacy of ICOS-4-1BB-ζ-CAR T cells may have relied solely on the incorporation of the ICOS transmembrane domain." (PMID 31108883, 2019). "Thus, ICOS expression is a potential biomarker for tumor response to ICIs although further studies are needed to establish its utility." (PMID 31192215, 2019). "ICOS (CD278) is a co-stimulatory molecule that plays an important role in tumor immunity." (PMID 31186477, 2019). "Moreover, the levels of PD-1 and ICOS markers expressed by CD8+CXCR5+ T cells were significantly higher in tumor tissue than in the matched blood or peritumoral liver tissues or in healthy blood samples." (PMID 31663864, 2019). "In addition, ICOS protects tumor cells from immune escape, and also play an important role in direct attack of antigen-specific cytotoxic T cells at the effector level." (PMID 29316975, 2018). "Furthermore, Fan and colleagues have described a functional role for ICOS in the anti-tumor immune response, providing a rationale for the combination of DC immunotherapy and engagement of ICOS-signaling in future treatments." (PMID 30245692, 2018). "Furthermore, young, but not elderly, IL-2/CD40-treated mice demonstrated additional reductions in other regulatory markers expressed by tumor-associated CD4+ T cells, including ICOS and IL-10." (PMID 30560130, 2018).
tumor (continued). "Here we demonstrate upregulation of ICOS expression on T cells following focal tumor radiation and test the hypothesis that ICOS agonism in combination with radiation will enhance the immunologic effect of radiation resulting in increased survival." (PMID 30400822, 2018). "In addition, the highest and most consistent ICOS expression was found on the tumor-infiltrating CD39+ Treg." (PMID 30651930, 2018). "Up-regulation of this activation marker may be evident long after treatment discontinuation, and a recent publication has indicated that the ICOS+ T cells may be the actual effector cells conveying the anti-tumour effect of Ipilimumab in a murine model." (PMID 28423678, 2017). "Thus, the infiltration of pDCs in neoplastic lesions favors the establishment of a tumor microenvironment by the activation and expansion of ICOS+ Tregs, accelerating disease progression." (PMID 29085361, 2017). "Assessment of expression of genes encoding the TNF receptor superfamily members as well as the immunoglobulin receptor superfamily revealed upregulation of genes encoding CD28, ICOS, 4-1BB, GITR, OX40, CD27 and CD40 within the NDV-injected tumours, with ICOS being most prominent." (PMID 28194010, 2017). "There appeared to be a concomitant increase in the absolute Tfh numbers in these tumours (defined by CD4+FoxP3-CXCR5+PD-1+ICOS+ lineage), although the relative percentage of these cells remained low and not substantially different from the other treatment groups." (PMID 28194010, 2017). "First, when the ICOS+ Teff to ICOS+ Treg ratio was measured mice receiving CTLA-4 blockade alone had a large tumor burden, thus the shift in ICOS+ Teff to ICOS+ Treg populations may no longer have been apparent." (PMID 26961085, 2016). "The data above indicated that Tregs (FOXP3+) cells were the major players in the tumour immunosuppressive microenvironment, and, more importantly, ICOS+ FOXP3+ cells were the majority, which was characterized by superior survival and highly suppressive properties." (PMID 27725696, 2016). "ICOS may therefore play a critical role in the tumor suppressive function exerted by Tregs in tumor-bearing mice." (PMID 23874581, 2013). "Other studies identified TNFR2, TIM-3, and ICOS as upregulated on Treg cells at tumor sites suggesting they may represent a distinct Treg cell subset that are generated specifically in response to TAA (52, –54, 56)." (PMID 23874336, 2013). "Finally, we analysed the expression of MiR101, a putative partner of ROQUIN involved in the modulation of ICOS expression and found similar levels of expression in tumor and reactive TFH." (PMID 23825522, 2013). "Therefore, our results are consistent with the previous findings and consolidate the notion that the presence of ICOS as an intracellular costimulatory signaling is crucial for enhanced T cell response to tumor cells." (PMID 23656794, 2013). "In epithelial ovarian cancer the majority of Foxp3+ Treg cells accumulating in the tumor microenvironment expressed the ICOS, and tumor pDCs expressing the ICOSL were shown to be essential for the expansion and suppressive function of these regulatory Foxp3+ Tregs." (PMID 24282405, 2013). "Thus, considering our experimental results, we can suggest that PTX may initiate an immunogenic remodeling of the tumor microenvironment, while ICOS-Fc further amplifies this response." (PMID 41471045, 2025). "Thus, these experiments highlight the effects of ICOS-Fc on the tumor microenvironment and underestimate the direct effects on tumor cells, which is nevertheless valuable since it releases the tumors potentially targeted by ICOS-Fc from the need to express ICOSL." (PMID 41471045, 2025). "Therefore, ICOS and PD-L1 may serve as more effective targets against activated Tregs, which elicit a more aggressive tumor-inhibitory immune response in the tumor microenvironment than non-activated Tregs." (PMID 40650080, 2025).
tumor (continued). "During the early phase of tumor growth (days 7–9), gp96 deletion induced a loss of Treg intratumoral infiltration and significantly augmented the activity of CD8+ TILs, as evidenced by increased CD44hiCD62lo, GZMB+Tcf-1–, ICOS+Tcf-1– effector cell populations and a Ki-67+ proliferating subset." (PMID 38787791, 2024). "A first approach was to develop agonist mAbs targeting ICOS that activate this signaling and exert anti-tumor activity by co-stimulating low ICOS+ Teff cells, thereby promoting activation and expansion of Teff cells, which in turn increase cytotoxic activity against tumor cells." (PMID 37215135, 2023). "Interestingly, selective analysis of the tumor-infiltrating T cells (of CD3+ cells instead of total cells) indicated that the ICOS/PD-1 combination therapy increased the percentage of cytotoxic CD8+ T cells and, at the same time, reduced the percentage of CD4+ effector cells." (PMID 36266600, 2023). "However, activation of ICOS/ICOS-L may also result in a pro-tumor response, mainly mediated by Treg cells." (PMID 36765704, 2023). "ICOS has an immune stimulatory effect, and patients with low levels of ICOS might demonstrate a good response to treatment strategies where the immune anti-tumor response is stimulated." (PMID 36980192, 2023). "The crucial role of ICOS for anti-tumor response elicited by CTLA-4-directed ICB renders ICOS as a potential biomarker to predict CTLA-4-directed ICB response and further for the stratification of patients who may benefit from immunotherapeutic ICOS-directed treatment." (PMID 37259155, 2023). "This study suggests that ICOS may be a potential tumor immunotherapy target and prognostic marker." (PMID 36855091, 2023). "Indeed, CD8+ T cells in the tumor periphery showed increased expression of genes belonging to costimulatory pathways, including ICOS, TNFRSF4 (OX40) and TNFRSF9 (4-1BB), albeit accompanied by high levels of inhibitory receptors PDCD1 (PD-1), LAG3, HAVCR2 (TIM-3), and CTLA4." (PMID 38127790, 2023). "Moreover, the ICOS/ICOS-L dyad may even play a role in anti-CTLA4 monoclonal antibody (mAb) anti-tumor activity, which results in an expansion of ICOS+ effector T cells, while its effect is significantly decreased in ICOS-/- mice." (PMID 36500861, 2022). "Therefore, using PD-1 and ICOS to enrich for tumor-reactive CD4+ Th cells prior to TIL expansion may be a way to increase the clinical success of adoptive T cell therapy." (PMID 35439168, 2022). "The finding that these Th cell–APC interactions occur in the tumor stroma, coupled with evidence for enrichment in Tfh cell content among the PD-1+ICOS+CD4+ TIL cohort, suggests that these lymphoid aggregates may represent one of the various maturational stages of TLSs." (PMID 35703176, 2022). "Furthermore, isolation of the DP PD-1+ICOS+ cell population could be used to enrich for tumor-reactive CD4+ Th cells for adoptive T cell therapy approaches." (PMID 35439168, 2022). "However, the effect of ICOS-Fc in the IL MIX is highlighted by the significant loss of the anti-tumor effects displayed in the IL MIX that lacked ICOS-Fc." (PMID 36500861, 2022). "Interestingly ICOS antibody was able to abrogate the significant increase in regulatory T cells associated with tumor radiation and thus negates one of the major negative regulatory mechanisms that occurs following radiation." (PMID 36056093, 2022). "CAR-T cells are personalized, genetically modified, anti-tumor T cells that have engineered pathways such as internalized T cell activating signaling proteins such as 4-1BB, OX40, and ICOS, and which may only activate through external anti-tumor antibody antigen attachment." (PMID 35208277, 2022). "Indeed, ICOS on T cells has been shown to favor the survival of effector-memory T cells promoting tumor immunity, and therefore, agonistic Abs targeting ICOS are under investigation in clinical trials for cancer immunotherapy, in combination with PD-1 blockade." (PMID 34912335, 2021).
tumor (continued). "The underlying mechanism could be that plasmacytoid DCs (pDCs) in the PTC microenvironment induces the transformation of initial CD4+T cells into FoxP3+ICOS+Tregs through the inducible costimulatory ligand (ICOSL)-ICOS pathway hence resulting in Tregs enrichment and tumor escape." (PMID 32626535, 2020). "Additionally, it is also suggested in 2017 that CD8+PD-1+Tim-3+Lag-3+ tumor-infiltrating lymphocytes, ICOS+ tumor-infiltrating Treg cells may be as significant factors for postoperative early relapse in localized RCC patients." (PMID 31956346, 2020). "Furthermore, α-TGFβ or α-PD-1 monotherapy elevated the percentage of CD8+ T cells that express markers of late T cell differentiation and partial T cell exhaustion, ICOS and CTLA4, that have also been associated with active anti-tumor responses in human tumors." (PMID 30832732, 2019). "Indeed, the major Treg subset in tumor expressed ICOS, such as papillary thyroid cancer and GC." (PMID 31777600, 2019). "Therefore, the combined mRNA expression of key signal transduction pathway components and regulators of the extracellular tumor microenvironment in combination with certain direct regulators of immune activity (ICOS, DPP4) appears to predict priming for responsiveness to CTLA-4 blockade." (PMID 28807052, 2017). "The related CD28 family member, inducible T-cell costimulator (ICOS), is inducibly expressed upon T cell activation, and preclinical data engaging ICOS via expression of ICOS-L in a vaccine preparation have shown anti-tumor effects in vivo [J.P. Allison, personal communication]." (PMID 24829752, 2013). "In addition, blocking the ICOS-pathway could inhibit the pDC-triggered proliferation of Treg within the tumor." (PMID 23763830, 2013). "However, as ICOS pathway also favors the differentiation of T helper(Th)-17 cells which might either promote tumor growth or antitumor response careful preclinical investigations of ICOS inhibitors (314.8 mAb) is needed." (PMID 23763830, 2013). "The tumor cells co-expressed ICOS and ICOSL, and the upregulated expression of ICOS and ICOSL reflected disease severity." (PMID 41683829, 2026). "Immune checkpoint blockade therapies, which target immune cells expressing CTLA4,CD28,ICOS and PD1 in the tumor microenvironment, represents a first-generation antibody-based therapy for cancer." (PMID 40027134, 2025). "ICOS interacts with its ligand, ICOS-L (B7-H2, CD275), which is expressed on various cells, including tumor cells and antigen-presenting cells in the tumor microenvironment." (PMID 40646580, 2025). "Candidates possibly involved in modulating T cell activity include CD28/CD80, ICOS/ICOSL, OX-40/OX-40L, and B7-H6/NKp30, but very little is known as to their role in tumor–immune communication." (PMID 40649953, 2025). "CD4 + ICOS + PDCD1+ (PD-1) T-cells, resembling T follicular helper (Tfh) cells were more common in HPV+ve tumours, as were CD4 + naïve-like T-cell clusters and KIT + NK-cells." (PMID 39757146, 2025). "Studies have suggested that compared to Tregs in peripheral blood, tumor-infiltrating Tregs exhibit more proliferative and immunosuppressive phenotypes, with increased expression of CTLA-4, CD25, GITR, 4−1BB, OX40, ICOS, LAG-3, TIM3, TIGIT, and PD-1." (PMID 40587482, 2025). "Recent studies have shown that ICOS+ CAR-T cells exhibit enhanced persistence, improved cytokine production, and more robust tumor cell killing." (PMID 40519924, 2025). "In murine models, butyrate was shown to inhibit anti‐CTLA‐4‐induced upregulation of CD80/CD86 on DCs and ICOS (CD278) on T cells, as well as suppress the accumulation of tumor‐specific and memory T cells." (PMID 41085102, 2025). "In contrast, within the Tumor-Immune enriched neighborhood (comprising ~50% tumor and ~50% stromal/immune cells), CD8+T- cells were enriched for Granzyme B and PD-1 whereas CD4+T- cells in this neighborhood were enriched for ICOS and PD-1." (PMID 41254766, 2025).